SMAD7 (SMAD family member 7)
Diseases named in the same sentence as SMAD7 in open-access papers (continued):
Sharing a sentence is not in itself a finding about the gene and the disease.
larynx cancer (1 paper, 2010). A primary or metastatic malignant neoplasm involving the larynx. "In larynx cancer, a similar relationship was found for Smad7 mRNA low expression." (PMID 20462450, 2010).
liver dysfunction (1 paper, 2011). "Interestingly, we found that deletion of Smad7 is associated with development of spontaneous liver dysfunction in the mouse." (PMID 21386907, 2011). "However, about 30% of Smad7liver-KO mice with high efficiency of Smad7 deletion had spontaneous liver dysfunction, demonstrated as low body weight, overall deterioration, and increased serum levels of AST and ALT." (PMID 21386907, 2011).
liver failure (1 paper, 2011). A liver disease characterized by the liver losing or has lost all of its function. "Collectively, these results indicate that deletion of Smad7 in the liver is able to induce apoptosis of hepatocytes, leading to spontaneous liver failure in the mouse." (PMID 21386907, 2011).
localized scleroderma (1 paper, 2021). Localized scleroderma is the skin localized form of scleroderma characterized by fibrosis of the skin causing cutaneous plaques or strips. "Ultraviolet A1 phototherapy can decrease SMAD7 gene expression in localized scleroderma, indicating that Smad7 plays an important role in its pathology." (PMID 34059951, 2021).
Lynch syndrome (1 paper, 2020). An autosomal dominant hereditary neoplastic syndrome characterized by the development of colorectal carcinoma and a high risk of developing endometrial carcinoma, gastric carcinoma, ovarian carcinoma, renal pelvis carcinoma, and small intestinal carcinoma. "Studies also show that SMAD7 gene polymorphisms are associated with CRC risk in patients with Lynch syndrome." (PMID 32899503, 2020).
mantle cell lymphoma (1 paper, 2012). Mantle cell lymphoma is a rare form of malignant non-Hodgkin lymphoma affecting B lymphocytes in the lymph nodes in a region called the ``mantle zone''. "However, gene expression profiling data across NHL showed that Chronic lymphocytic leukemia (CLL) and Mantle cell lymphoma (MCL) had lower levels of SMAD6 and SMAD7, compared to the other B-cell malignancies." (PMID 23049692, 2012).
nephrotoxicity (1 paper, 2017). Toxicity that causes injury to the kidney or damages its function. "Also, BMPR1A, SMAD7, SMURF1 have been reported to be related to kidney fibrosis which is one key indicator of kidney nephrotoxicity." (PMID 28414804, 2017).
neurosyphilis (1 paper, 2017). Infection of the brain or spinal cord by Treponema pallidum. "Strikingly, the expression of Smad7, a negative regulator of the TGF-β signaling pathway, was significantly suppressed in the neurosyphilis patients." (PMID 29167762, 2017).
oral cancer (1 paper, 2025). "Tat-Smad7 does not impairthe therapeutic efficacy of radiotherapy on adjacent oral cancer cells, instead increasing oxidative stress and apoptosis, supportingits safe use in clinical oncology settings." (PMID 40636216, 2025).
oral epithelial dysplasia (1 paper, 2017). "By immunohistochemical staining, Smad7 was gradually increased in mild oral epithelial dysplasia moderate to severe oral epithelial dysplasia, lesions of hyperkeratosis/epithelial hyperplasia, moderately to poorly differentiated OSCC, and well-differentiated OSCC." (PMID 28708091, 2017).
osteoradionecrosis (1 paper, 2011). Necrosis of bone following radiation injury. "Osteoradionecrosis-affected tissues showed upregulation of TGFβ1 and Smad-2/3 expression and suppression of Smad-7; this was the opposite of findings in BRONJ-affected tissues." (PMID 21726429, 2011). "The pattern of Smad-7 expression differed between the specimens from normal, BRONJ-associated, and the osteoradionecrosis-related samples." (PMID 21726429, 2011). "In contrast, osteoradionecrosis-related mucoperiosteal tissue showed only a few Smad-7-stained cells." (PMID 21726429, 2011). "Smad-7 was significantly increased (p < 0.031) in the BRONJ group and significantly decreased (p < 0.026) in the osteoradionecrosis group." (PMID 21726429, 2011). "Thus, compared to control tissues, the overall density of Smad-7-expressing cells was significantly increased in BRONJ tissue (p < 0.031) and significantly decreased (p < 0.026) in the osteoradionecrosis-related tissue." (PMID 21726429, 2011).
pancreatic adenocarcinoma (1 paper, 2016). "SMAD7, an endogenous inhibitor of SMAD signaling, has been found to be overexpressed in pancreatic adenocarcinoma cells compared to healthy pancreatic tissue, but its expression and role in human PSCs is not known." (PMID 27473228, 2016).
Parkinson disease (1 paper, 2024). A progressive degenerative disorder of the central nervous system characterized by loss of dopamine producing neurons in the substantia nigra and the presence of Lewy bodies in the substantia nigra and locus coeruleus. "Consequently, SMAD7 presents as a promising target for therapeutic interventions aimed at addressing postmenopausal osteoporosis and Parkinson’s disease." (PMID 39840278, 2024).
pneumococcal infection (1 paper, 2018). Infections with bacteria of the species streptococcus pneumoniae. "Moreover, SPY1 vaccination elevated the levels of Smad2/3 and phosphor-Smad2/3 and downregulated the negative regulatory factor Smad7 in a time-dependent manner during pneumococcal infection, and these changes were reversed by P17 treatment." (PMID 30116243, 2018).
pouchitis (1 paper, 2025). Acute inflammation in the intestinal mucosa of the continent ileal reservoir (or pouch) in patients who have undergone ileostomy and restorative proctocolectomy (proctocolectomy, restorative). "Enhanced Smad7 expression was seen in the inflamed pouch of patients with CP compared to the normal or inflamed ileum of the same patients and the uninflamed pouch of patients with no pouchitis and normal controls." (PMID 40098948, 2025).
preeclampsia (1 paper, 2021). Preeclampsia is a hypertensive disorder of pregnancy that is characterized by new-onset hypertension with proteinuria presenting after 20 weeks of gestation, and depending on mild or severe forms may initially present with severe headache, visual disturbances, and hyperreflexia. "Phosphorylated SMAD2 and SMAD7 expression are also increased in early onset preeclampsia as compared with an age matching control." (PMID 33673360, 2021).
prostatitis (1 paper, 2021). An infectious or non-infectious inflammatory process affecting the prostate gland. "In addition, DHA and BMMSC cotreatment dose-dependently suppressed the downregulation of Smad7 induced by prostatitis." (PMID 34956376, 2021).
retinal detachment (1 paper, 2008). An eye emergency condition which may lead to blindness if left untreated. "Injury induced tissue fibrosis in the crystalline lens or fibrosis in the retinal pigment epithelium after producing experimental retinal detachment were prevented by the adenoviral gene transfer of Smad7 or dominant-negative p38MAPK in mice." (PMID 19081766, 2008).
rhinitis (1 paper, 2018). An inflammation of the mucous membrane lining the nose, usually associated with nasal discharge. "However, whether Smad7 was involved in regulating LPS-induced cell injury in rhinitis remain unclear." (PMID 29433423, 2018).
spinal tuberculosis (1 paper, 2023). "It is possible that miR-543 can regulate the expression of Dickkopf 1, Smad7, and other proteins in spinal tuberculosis lesions, mediate YAP, and affect bone formation." (PMID 36926516, 2023).
Stroke (1 paper, 2024). Sudden impairment of blood flow to a part of the brain due to occlusion or rupture of an artery to the brain. "SMAD7 exhibits the strongest association with PD, NM, AD, and Stroke." (PMID 39840278, 2024).
systemic sclerosis (1 paper, 2020). A chronic disorder, possibly autoimmune, marked by excessive production of collagen which results in hardening and thickening of body tissues. "Deregulation of Smad7 expression has been associated with various human diseases, such as tissue fibrosis or systemic sclerosis." (PMID 32295230, 2020).
vitamin A deficiency (1 paper, 2016). Deficiency of vitamin A due to malnutrition, malabsorption, or dietary lack. "Compared to the control group, vitamin A deficiency down-regulated Hamp (2.3-fold, p < 0.001) and Smad7 (1.6-fold, p = 0.027) mRNA levels in the liver and up-regulated hepatic Hfe2 (1.2-fold, p = 0.026) and Bmp6 mRNA levels (2.0-fold, p = 0.0013)." (PMID 27551308, 2016). "Vitamin A deficiency (VAD) increased hepatic Bmp6 and Hfe2 mRNA levels and down-regulated hepatic Hamp, Smad7, Rarα, and intestinal Fpn1 mRNA levels compared with the control." (PMID 27551308, 2016).
tumor (214 papers, 2006 to 2026). "Consistently, Smad7 mRNA and protein expression were significantly reduced in xenografts that were generated by the inoculation of Stat3-deficient tumor cells into BALB/cnu/nu mice." (PMID 36291778, 2022). "Reduced levels of SDC2 in TASCs was associated with a significant decrease in tumour growth compared to that of shControl tumours and reduced levels of TGFβ‐regulated genes, for example, SMAD7." (PMID 33152121, 2021). "The low expression of IL17A caused by the Smad7 expression in tumor-infiltrating CD4(+) T cells enabled the TNF-α-mediated killing of cancer cells both in vitro and in vivo." (PMID 34059951, 2021). "Interesting, the tumor-promoting effects of Smad7 are linked to activation of NFκB and Stat3 signaling in these mouse models." (PMID 31614569, 2019). "An analysis of 150 invasive breast cancer specimens showed that Smad7 expression positively correlated with tumor stage and size, and associated with an aggressive phenotype." (PMID 31052449, 2019). "We also found that low SMAD7 protein expression was associated with tumor grade: when SMAD7 expression was lower, the cancer grade was higher." (PMID 31711043, 2019). "Then, SMAD7 was chosen for further study from the candidate target genes as previous studies have demonstrated that SMAD7 was associated with tumor invasion and metastasis." (PMID 30154401, 2018). "Using micro-computed tomography analysis, we indeed demonstrated that Smad7 inhibits tumor-associated bone destruction by both promoting ectopic bone formation and preventing trabecular bone osteolysis." (PMID 27827889, 2016). "Using a mouse model of HCC induced by diethylnitrosamine (DEN), Wang and colleagues showed that Smad7-deficient mice had higher tumor incidence and multiplicity than wild-type mice." (PMID 24317436, 2013). "Amongst clinicopathological parameters, loss of Smad7 significantly correlated with both tumor size as well as margin status." (PMID 22195733, 2011). "Loss of Smad7 expression correlated significantly with tumor size (r = 0.421, p < 0.036) and margin status (r = 0.431; p < .032)." (PMID 22195733, 2011). "Our results showed that PHF14 expression was inversely associated with the level of SMAD7 in tumor specimens with high DNMT3B expression, and by contrast, the correlation between the expression levels of PHF14 and SMAD7 was not significant in those expressing low DNMT3B." (PMID 37072414, 2023). "In addition, miR-545-3p, a tumor promoter targeting both circFGGY and Smad7, suppressed the upregulation of Smad7 caused by circFGGY overexpression." (PMID 35592246, 2022). "Interestingly, low promoter methylation of SMAD7 was associated with lower tumor grade but high recurrence rate (p < 0.001) and metastasis (p = 0.05)." (PMID 34571856, 2021). "Overexpression of Smad7 in tumour-associated fibroblasts may therefore result in their unresponsiveness to TGFβ signalling." (PMID 24090133, 2013). "The current results revealed that aberrant TGF-β1 was associated with Smad2 and Smad7 expression in tumor tissues, and that direct coculture GC cells with PBMCs could promote the expression of Smad2 and Smad3." (PMID 23342108, 2013). "Similar to Smad4, normal pancreatic tissue showed moderate to high levels of Smad7 expression in most of the samples (18/25, 72%), whereas, more than half of tumor tissue showed complete loss of protein expression (4/25, 56%), and another 24%(6/25) of cases showed low expression." (PMID 22195733, 2011). "Additionally, the rs12953717 of SMAD7, which was reported in 2 GWAS studies, may be valuable markers for predicting the risk of tumor formation." (PMID 26579801, 2015).
tumor (continued). "Integration of GWAS and RNA-seq revealed that 24 CRC-associated genes, including PYGL, SMAD7, and TCF7L2, are involved in tumor metabolism and Wnt/TCF signaling." (PMID 41144378, 2025). "CHLD has been found to regulate the expression of proteins Smad3 and Smad7 in the TGF-β1/Smad pathway to inhibit tumor proliferation in tumor-bearing mice with renal cell carcinoma." (PMID 39239653, 2024). "While CARM1 regulates arginine methylation of Smad7 in tumor proliferation, rhArg and ARC are essential for MR in the arginine synthesis pathway." (PMID 38841622, 2024). "Through the process of enhancing small cell lung cancer (SCLC) tumor growth, coactivator-associated arginine methyltransferase 1 (CARM1) regulates arginine methylation of Smad7." (PMID 38841622, 2024). "In CRC, SMAD7 enhances cell growth and survival, and indirect evidence suggests the involvement of SMAD7 in tumor progression and metastatic dissemination." (PMID 39001432, 2024). "Research indicates that TGF-β can suppress the activity of M1 macrophages, the main components exerting anti-tumor immune responses among macrophages, through the Smad7 and TNF pathways." (PMID 38767747, 2024). "Sma-and mad-related protein 7 (SMAD7) can affect tumor progression by closing transforming growth factor-beta intracellular signaling channels." (PMID 36607878, 2023). "The tumor we studied were also constrained to CRC; more research is needed in the future to explore the correlation between SMAD7 polymorphisms and cancer susceptibility further." (PMID 36607878, 2023). "Smad7 acts as a tumor suppressor in HCC by inhibiting cell growth while triggering programmed cell death." (PMID 36740668, 2023). "ATXN7L3 also promotes SMAD7 transcription through the regulation of histone H2B ubiquitination levels and is subsequently involved in the inhibition of tumour growth in HCC." (PMID 37685308, 2023). "As a tumor suppressor gene in the early stage and a tumor promoter gene in the late stage, SmAD7 is positively correlated with the degree of malignancy." (PMID 36969909, 2023). "In summary, miR-424-5p participates in the EMT of ESCC cells through the Smad7 signaling pathway, which leads to tumor proliferation, invasion and migration and exists as an antitumor factor in ESCC." (PMID 35409396, 2022). "UPF1 acts, in part, by destabilizing the NMD substrate encoding the TGFβ inhibitor, Smad7, and stimulating TGF signaling, and several studies have shown that UPF1 exerts suppressive roles in tumor progression." (PMID 35338348, 2022). "Studies in human tumor cell lines have previously shown that the tumor-associated overexpression of EGFR results in the sustained hyperactivation of Stat3, which eventually induces Smad7 expression." (PMID 36291778, 2022). "Taken together, the literature on the involvement of SMAD7 in tumor progression has reported contradictory data about its protumorigenic or antitumorigenic role in different types of cancer." (PMID 35912252, 2022). "To further explore the influence of circFGGY/miR-545-3p/Smad7 axis in tumor growth in vivo, we established a mouse HCC model." (PMID 35592246, 2022). "In line with previously published data, both Smad7-positive cells and p-Stat3-positive cells were more abundant in the tumor tissue, compared to the normal mucosa of CRC patients." (PMID 36291778, 2022). "We have previously demonstrated that the combination treatment of AA and NG can effectively rebalance the Smad3 and Smad7 signaling in the acute kidney injury model 9 and tumor microenvironment." (PMID 36147472, 2022). "TGFβ signaling cascade alterations, such as mutations affecting SMAD proteins or the blocking of their phosphorylation process by the inhibitory SMADs, SMAD6 and SMAD7, have been proved to be related to tumor progression." (PMID 33498521, 2021). "In vitro, syndecan‐2 modulated TGFβ signalling (SMAD7, PAI‐1), migration and immunosuppression of patient‐derived tumour‐associated stromal cells (TASCs)." (PMID 33152121, 2021).